PLGRKT (plasminogen receptor with a C-terminal lysine)
Description:
Receptor for plasminogen. Regulates urokinase plasminogen activator-dependent and stimulates tissue-type plasminogen activator-dependent cell surface plasminogen activation. Proposed to be part of a local catecholaminergic cell plasminogen activation system that regulates neuroendocrine prohormone processing. Involved in regulation of inflammatory response; regulates monocyte chemotactic migration and matrix metalloproteinase activation, such as of MMP2 and MMP9.
Synonyms: Plg-R(KT); C9orf46; AD025; MDS030; FLJ14688; Plg-RKT
Tractability: Antibody: UniProt places it where antibodies can reach, with high confidence; UniProt predicts a signal peptide or a membrane-spanning region; its Gene Ontology location is reachable by antibodies, with medium confidence. PROTAC: its protein half-life has been measured.
Gene: Protein-coding gene on chromosome 9 (5,357,966 to 5,438,615, reverse strand). Ensembl gene ENSG00000107020.
Subcellular location: Cell membrane
Subcellular location (Human Protein Atlas): Mitochondria
Gene Ontology:
Molecular function: protein binding
Biological process: positive regulation of plasminogen activation
Cellular component: mitochondrion; plasma membrane
Genetic constraint (gnomAD): Loss-of-function variants: 11 observed, 6.39 expected, observed/expected ratio (o/e) 1.72, 90% interval 1 to 1.95. That is too few expected variants to judge how well the gene tolerates losing a copy. Missense variants: 77 observed, 57.67 expected, observed/expected ratio (o/e) 1.34, 90% interval 1.11 to 1.61. Synonymous variants: 18 observed, 15.89 expected, observed/expected ratio (o/e) 1.13, 90% interval 0.78 to 1.66.
Homologues: Orthologues: chimpanzee PLGRKT (100% identical), macaque PLGRKT (95% identical), dog PLGRKT (90% identical), rabbit PLGRKT (86% identical), rat Plgrkt (86% identical), pig PLGRKT (84% identical), guinea pig PLGRKT (83% identical), mouse Plgrkt (82% identical), zebrafish plgrkt (63% identical), tropical clawed frog rflb (53% identical), Drosophila melanogaster CG13404 (27% identical), Caenorhabditis elegans tag-280 (23% identical), and 1 more.
Diseases named in the same sentence as PLGRKT in open-access papers:
PLGRKT is named in the same sentence as 13 diseases in open-access papers, as found by Europe PMC text mining. Sharing a sentence is not in itself a finding about the gene and the disease. The quoted sentences say what the papers report.
breast carcinoma (2 papers, 2024 to 2025). "By systematically integrating efferocytosis- and invasion-related genes, this study identified ANO6 and PLGRKT as dual-process-driven prognostic biomarkers in breast cancer." (PMID 40762681, 2025). "In conclusion, the developed prognostic risk model effectively predicts survival outcomes in patients with breast cancer, with ANO6 and PLGRKT being pivotal in tumor progression." (PMID 40762681, 2025).
Insulin resistance (1 paper, 2023). Increased resistance towards insulin, that is, diminished effectiveness of insulin in reducing blood glucose levels. "In genome-wide association studies, the human PLGRKT (C9orf46) gene was identified as a novel genetic locus for the pathophysiology of childhood obesity and has also been found to be associated with polycystic ovarian syndrome, which in turn is associated with obesity, insulin resistance, and T2D." (PMID 37642146, 2023).
ovarian carcinoma (1 paper, 2024). A malignant neoplasm originating from the surface ovarian epithelium. "VPS13B, TBC1D22A, PPP3CA, CUX1 and PPP1R15A were identified as poor prognostic genes for cisplatin resistance in ovarian cancer, while PLGRKT, CDKAL1 and TAP1 were identified as good prognostic genes." (PMID 39103807, 2024). "Through biological information screening, RT-qPCR and WB verification, it was found that VPS13B, TBC1D22A, PPP3CA, CUX1 and PPP1R15A were highly expressed in cisplatin-resistant tissues of ovarian cancer, while PLGRKT, CDKAL1 and TAP1 were low expressed." (PMID 39103807, 2024). "VPS13B, TBC1D22A, PPP3CA, CUX1 and PPP1R15A were identified as poor prognostic genes of cisplatin resistance in ovarian cancer, while PLGRKT, CDKAL1 and TAP1 were identified as good prognostic genes." (PMID 39103807, 2024).
type 1 diabetes (1 paper, 2025). "Among the 285 disease-associated genes, CD69, PLGRKT, and CD226 have also been implicated in recent genome-wide association studies (GWAS) of type 1 diabetes, highlighting the potential significance of these genes in type 1 diabetes." (PMID 41462339, 2025).
tumor (4 papers, 2021 to 2025). "Correlation analysis demonstrated that gene expression, except for PLGRKT, was significantly associated with immune cell infiltration, implying that these genes may have a potential role in shaping the tumor immune microenvironment." (PMID 37713839, 2023). "These interactions suggest a coordinated mechanism: ANO6-mediated ion dyshomeostasis primes early metastatic niche formation, while PLGRKT loss exacerbates ECM stiffness and inflammatory signaling, collectively fueling tumor progression." (PMID 40762681, 2025).
PLGRKT also shares sentences with these, for which no sentence is quoted: gastric cancer (2 papers); anal carcinoma (1); cancer (1); hypothyroidism (1); invasive ductal carcinoma (1); melanoma (1); Obesity (1); polycystic ovarian syndrome (1).